MOSPD3 (motile sperm domain containing 3)
Synonyms: CDS3; NET30
Tractability: Antibody: UniProt predicts a signal peptide or a membrane-spanning region.
Gene: Protein-coding gene on chromosome 7 (100,612,102 to 100,615,983, forward strand). Ensembl gene ENSG00000106330.
Subcellular location: Membrane
Subcellular location (Human Protein Atlas): Cytosol
Gene Ontology:
Molecular function: protein binding
Cellular component: membrane
Genetic constraint (gnomAD): Loss-of-function variants: 20 observed, 24.76 expected, observed/expected ratio (o/e) 0.81, 90% interval 0.57 to 1.17. The upper end of that interval is the gene's LOEUF score, 1.17, which puts it in group 5 of 6, group 1 being the genes least tolerant of losing a copy. Missense variants: 307 observed, 334.28 expected, observed/expected ratio (o/e) 0.92, 90% interval 0.84 to 1.01. Synonymous variants: 136 observed, 144.31 expected, observed/expected ratio (o/e) 0.94, 90% interval 0.82 to 1.09.
Homologues: Orthologues: chimpanzee MOSPD3 (98% identical), macaque MOSPD3 (98% identical), guinea pig MOSPD3 (93% identical), dog MOSPD3 (91% identical), rat Mospd3 (89% identical), mouse Mospd3 (89% identical), pig MOSPD3 (87% identical).
Diseases named in the same sentence as MOSPD3 in open-access papers:
MOSPD3 is named in the same sentence as 1 disease in open-access papers, as found by Europe PMC text mining. Sharing a sentence is not in itself a finding about the gene and the disease. The quoted sentences say what the papers report.
infection (1 paper, 2023). The state of being infected such as from the introduction of a foreign agent such as serum, vaccine, antigenic substance or organism. "In particular, MoSPD2 was expressed mainly at late time points of infection (e.g., 60 to 72 hpi), while MoSPD3/MoBAS52 was more expressed at the early time points (e.g., 24 to 32 hpi)." (PMID 38298608, 2023).